CD68 (CD68 molecule)
Diseases named in the same sentence as CD68 in open-access papers (continued):
Sharing a sentence is not in itself a finding about the gene and the disease.
tumor (continued). "The tumor was composed of atypical spindle cells that were partly positive for cytokeratin AE1/3, CAM5.2, and vimentin and scattered osteoclast-like multinucleated giant cells that were positive for CD68." (PMID 40230762, 2025). "However, the dynamics of different macrophage subsets, particularly CD68+ and CD163+ populations, in relation to tumor thickness and stage remain insufficiently characterized." (PMID 41007741, 2025). "As observed for Rep staining, IHC staining for anti-CD68 revealed no visible difference in macrophage staining intensity between paired tumor-distant and peritumor tissues, or among tumor-distant tissues taken at different distances from the primary tumors." (PMID 40136704, 2025). "In our study, we observed increased infiltration of both CD68 and CD206 positive cells suggesting a higher presence of M2-type tumor-associated macrophages (TAMs) in tumors lacking MCPIP1 RNase activity." (PMID 39815326, 2025). "High rates of CD68+CD163− (p = 0.044), CD68+CD163+, and CD68+CD206+ macrophages (p < 0.001) were significantly favorable for 10-year DFS only in the stromal compartment of tumor-distant normal tissue." (PMID 40498004, 2025). "In this regard, a study on pre-treated PM patients found that PD-1-expressing CD8+ T cells and CD68+ macrophages, but not PD-L1-expressing tumor or immune cells, were independent predictors of response to pembrolizumab." (PMID 41463268, 2025). "Increasing ISG15+ cells were detected in both the tumour region and normal bowel wall of patients with partial response for ICI treatment, whereas ISG15+ CD68+ macrophages were only enriched in the normal bowel wall, indicating their proinflammatory phenotypes in the bowel wall." (PMID 39934971, 2025). "EGFR and IDH1 were highly expressed in tumor cells, FAP and COL1A1 were confined to fibroblasts, CD68 and ITGAM marked macrophages, PECAM1 and CDH5 identified endothelial cells, OLIG2 and MOG were specific to oligodendrocytes, while CD4 and CD3D defined T-cell subsets." (PMID 41208987, 2025). "Therefore, we investigated Bcl-2 expression in CD68+CD86+ M1 macrophages in DLBCL samples (intra-T vs peri-T) and in DLBCL vs non-tumor control lymph node samples." (PMID 41415285, 2025). "Furthermore, CD68+ and MPO+/CD206+ cells with round nuclei (likely M2 macrophages) were generally localized at the tumor periphery, with some in the intratumoral regions, suggesting that most of the infiltrating MPO+ cells were TANs." (PMID 40751595, 2025). "One was a nonepithelial tumor comprising immature spindle-shaped and stellate plaques, with positivity for the mesenchymal markers vimentin and CD68 and negativity for myogenic, neurogenic, and other markers." (PMID 40755904, 2025). "In contrast, CD14+ monocytes and CD163+ and CD68+ macrophages predominated in the immune landscape of the FGF23-secreting tumour microenvironment, accounting for 30.74%, 23.23%, and 16.96% of all detectable immunopositive tumour cells, respectively." (PMID 40981193, 2025). "These structures could be visible by staining, including panel I: CD8+ T cells, CD4+ T cells, PD-1+ cells, PD-L1+ cells, Foxp3+ regulatory T cells; and panel II: CD19+ B cells, CD56+ NK cells, CD68+ macrophages, CD163+ M2 macrophages, cytokeratin+ tumor cells." (PMID 38637495, 2024). "There was a significant increase in CD8+ and CD68 + T-cell infiltration from baseline tumor samples to day 5 of treatment (CD8: Wilcoxon signed-rank test V = 57, P = 0.032, n = 11, CD68: Wilcoxon signed-rank test V = 56, P = 0.042, n = 11), but not of CD4+ cells." (PMID 38216554, 2024). "MIHC staining revealed that SPP1 was substantially colocalized with CD68+ cells but barely colocalized with CD4+ T cells, CD8+ T cells or B cells and that SPP1 was more highly expressed in macrophages derived from HNSCC tumor tissues compared with those derived from adjacent normal tissues." (PMID 39726047, 2024).
tumor (continued). "In this study, we observed that neither CD68+CD86+SHP2+ TAMs nor CD68+CD206+SHP2+ TAMs in tumor region were indicative of prognosis within the patient cohort." (PMID 38799432, 2024). "However, the regression analysis only showed a significant correlation between tumor volume and tumor growth rate as well as IRF4 and CD68 mRNA levels with growth rate having the strongest influence on tumor volume." (PMID 39272860, 2024). "The population of non-polarized macrophages (CD68 + CD206-iNOS-) was also determined for each of the tumor regions." (PMID 38956203, 2024). "Thus, CD47, CD68, and CD163 not only serve as prognostic indicators but also represent promising targets for novel cancer therapies designed to modulate the tumor immune microenvironment." (PMID 39682556, 2024). "Additionally, we conducted an analysis on the correlation between CD68+SHP2+ TAMs and CD68+CD206+TAMs in TME, including stroma and tumor regions, which yielded consistent results." (PMID 38799432, 2024). "Nearest-neighbor analysis revealed that both immunosuppressive and proinflammatory macrophages are nearest PanCK+ tumor cells, CD14+ myeloid cells, and other CD68+ macrophages and are farthest from CD66b+ neutrophils and CD3+ T cells in the TME of bone metastases." (PMID 38193534, 2024). "Tumor infiltration by CD8 and CD68 was assessed through immunohistochemistry." (PMID 39330005, 2024). "Tregs and macrophages (CD68 and CD163) are more complicated since some data suggested Treg and macrophage infiltration in the tumor microenvironment might be poor prognostic markers, but another study suggested they might be favorable prognostic markers." (PMID 38339307, 2024). "Tumour macrophage numbers were not related to HIV status, but low pro-inflammatory (M1) macrophage numbers (CD68 + CD163 −) were significantly associated with poorer outcomes (HR 2.02, p = 0.03)." (PMID 39259401, 2024). "In the tumor spots, Rep detection was generally weaker and did not specifically correlate with the localization of CD68+ Mfs." (PMID 36811271, 2024). "Furthermore, we observed a high expression of CD8 (a marker of CD8+ T cells) and CD68 (a marker of macrophages) in NAT, while their presence was almost undetectable in the tumour." (PMID 38804617, 2024). "Notably, the levels of CD68 + CD163-, indicative of M1 macrophages, were higher in the primary MEN1/DAXXmut (PM) group compared to its metastatic (MM) counterpart (p = 0.280 in tumor, p = 0.332 in stroma)." (PMID 38448900, 2024). "More than one tumour had high/very high levels of the myeloid suppression markers CSF1R and CD68." (PMID 35866362, 2024). "Immunohistochemically, the tumor cells were positive for CD68 and vimentin, but were negative for epithelial membrane antigen, cytokeratin, and additional muscle markers." (PMID 38515205, 2024). "Spatial analysis of cell phenotypes revealed that CD14+ myeloid cells and CD68+ macrophages were significantly enriched in the stromal tissue of bone metastases rather than the tumor tissue." (PMID 38193534, 2024). "While the low frequency of Tregs was associated with improved PFS in the tumor microenvironment, no predictive value of CD8, CD68, CD163, PD-1 and PD-L1 expression was observed in our study." (PMID 38339307, 2024). "As for the stroma, MHC-II expression on tumor cells was associated with the presence of high total immune cells (p=0.026) and high CD4+ TH (p=0.026), but not with CD8+ CTL (p=0.072) and CD68+ cells (p=0.062)." (PMID 39035008, 2024). "We propose a model in which the relative ratio of specific bacterial genera constitutes a rheostat, that shapes the immune microenvironment, inversely correlating with CD68+ myeloid cell infiltration to likely enable efficient CD8+ T-cell infiltration, activation, and clinical tumour suppression." (PMID 39168966, 2024).
tumor (continued). "Alternatively, we showed that anti-mouse CD68 IHC of aEGFRvIII-SGRP CAR-treated brains on day 13 post-tumor implantation (compared to day 21 for all other conditions) had a more pronounced density of GAMs on sites of tumor scarring." (PMID 39521782, 2024). "Analysing the relevance of PHD2 in immune cells for tumour development, Phd2 was deleted in haematopoietic cells (CD68-Cre) and the mice were inoculated with LLC cells, leading to reduced tumour growth, decreased tumour cell apoptosis and enhanced proliferation." (PMID 38509356, 2024). "Furthermore, mIF results indicated that the patients with ITGAL-high expression tend had significantly higher CD8+ T cells, CD68+ macrophages, CD4+ T cells, and CD20+ B cells infiltration in their tumor tissues." (PMID 38646528, 2024). "In this study, we found that the CTLA4, CD68, and CD4 genes were closely related to THC and CMS1 CRC; therefore, this suggested that CHCs and THCs may act as a new marker of immunotherapies in tumor treatments in the future." (PMID 39499374, 2024). "Immunohistochemistry reveals CD68, CD163, lysozyme, and CyclinD1 expression in the tumor cells." (PMID 38706599, 2024). "Likewise, overweight/obese patients showed a strong tendency for higher numbers of CD68+ (1.8-fold, p = 0.119) and CD163+ (3.80-fold; p = 0.062) cells in the tumor tissue." (PMID 39456610, 2024). "M1 macrophages have anti-tumor activity and are characterized by the expression of CD68, 80, 86, and MHC-II, and M2 macrophages that promote tumor growth and are characterized by the expression of CD163, 204, 206, and secretion of immunosuppressive cytokines such as IL-10 and tumor growth factor-β." (PMID 39624236, 2024). "Cytokeratin was strongly positive only in the tumor cells and negative in the giant cells, while CD68 was strongly positive only in the giant cells and negative in the tumor cells." (PMID 38957813, 2024). "Whilst Juzentaihoto alone did not significantly alter CD68+ macrophage infiltration, we observed an increase upon Gemcitabine treatment, especially at the tumor border, which was even higher in the Gem/Juz combination treatment." (PMID 39723364, 2024). "Through immunohistochemical staining with CD206 and CD66b, as well as flow cytometric analysis of CD68 + CD206+ (M2 macrophages) and CD14 + CD66b+ (neutrophils), we found that BNST tumor samples exhibited a higher accumulation of M2 macrophages (M2 mac) and a lower presence of neutrophils (neu)." (PMID 38331905, 2024). "Twelve patients with a CD68/CD163 ratio > 1 in the tumor center showed significantly longer OS than those without dominant M1-polarized macrophages." (PMID 39630300, 2024). "Activation of CD68-positive microglia and the formation of so-called immune cell “nodules” containing CD3- and CD8-positive T-cells in the tumor tissue could be demonstrated." (PMID 39340558, 2024). "We used CD68 to locate macrophages in HCC tissues and stain the markers of M2 macrophages in order to explore whether macrophages and other cells in the tumor microenvironment are involved in the high expression of IL-41 and the malignant progression of HCC." (PMID 38835390, 2024). "A more targeted analysis of innate immune cell subsets revealed subsets of CD14+ macrophages (CD16+ CD68+ CD206+ CD11c+/–) were significantly higher within tumor compared with nontumor regions." (PMID 39761010, 2024). "Unfortunately, in malignant tumor tissues, CD68+ macrophages are mostly located in the stroma region away from tumor cells, while NKp46+NKT cells are mostly located in the tumor region close to tumor cells, which reduces the opportunity for effective interaction between the two types of cells." (PMID 38279145, 2024). "The remaining subjects in the immune-reconstituted vehicle control group were caspase negative, as tumor cells were not present, although an increase in CD-3, CD-4, and CD-68 staining was observed in the tumor transplant area." (PMID 39200298, 2024).
tumor (continued). "CD163 + and CD206 + TAMs are particularly enriched at the tumor invasion front, correlating with vascular density, whereas CD68 + cells show no regional differences." (PMID 39068459, 2024). "Our findings indicated a significantly (p < 0.05) higher expression of protein biomarkers associated with the presence and activity of immune cells, including CD45, CD3, CD68, CD163, CD11c, CD8, HLA-DR, CD40, PD-L1, and IDO1, in the tumor compartments of patients with CR compared to those with PD." (PMID 39049036, 2024). "We did not observe any prognostic role of baseline CD8, CD68 or CD163 expression in the tumor microenvironment." (PMID 38339307, 2024). "In a study applying digital spatial profiling, PD-L1 expression in the CD68+ (macrophage) compartment but not in the tumor compartment proved predictive of immunotherapy effects." (PMID 39766316, 2024). "Summarily, CD8, CD68, CD206, MIF, and CXCR4 expression are related with tumor progression." (PMID 39464891, 2024). "We detected CD68+ TAMs in all tumour sections, with no overt differences in density noted between treatment groups." (PMID 38622286, 2024). "In addition, the expression levels of CD163, CD68, CD44, and CD133 in GBC tissues were significantly correlated with tumor metastasis." (PMID 39138521, 2024). "Given that these genes could potentially influence the tumor purity of DLBCL, we then analyzed the relationship between them and CD68 + macrophages, CD4 + T cells, and CD8 + T cells." (PMID 38980810, 2024). "A high proportion of CD68+ PD-L1+ and CD68+ IDO-1+ TAMs is associated with a poor prognosis, while the presence of PD-L1+ tumor cells, total TAMs, PD-L1- TAMs, or IDO-1- TAMs does not affect the prognosis." (PMID 38779660, 2024). "Additionally, in the in vivo experiments, increases in CD68+/CD80+ and CD68+/CD86+ cells around the tumor region imply that Nb‐TriTE attracts or activates macrophages (particularly M1) or dendritic cells." (PMID 39234811, 2024). "Moreover, the Spearman correlation test revealed a strong positive correlation between hormone receptor status and the tumor features of BC cells and the CD45- and CD68-positive regions." (PMID 38833004, 2024). "In our study, we first analyzed the heterogeneity of TAMs in OS tissues based on single-cell data and identified three types of TAMs, CD68 + TAMs, AHR + TAMs, and M0 TAMs, which confirmed that the distribution of M1/M2 macrophage polarization was ambiguous in the actual tumor environment." (PMID 38280909, 2024). "Microglia/macrophage motility and activation (Iba1, CD68), programmed death-ligand 1 and CD4+ T cells were reduced, and homeostatic microglia (P2RY12) were increased in the invasive margins compared with the tumour core." (PMID 37324244, 2023). "We also identified that the frequencies of subsets of tumor cells, CD4+ T cells, CD45RO+, stroma, and CD68+ macrophages, which are selected by S3-CIMA compared with non-selected cells from the same cell types, are significantly higher in the DII than in the CLR group." (PMID 37720335, 2023). "In the absence of a CD68 antibody suitable for immunohistochemistry in canine tissue, we verified the presence of macrophages in tumor tissue using Iba-1, a marker for macrophages in dogs." (PMID 36508875, 2023). "Notably, we found expression of the macrophage marker CD68 after 14 d of 3D culture, highlighting that our TME model recreates tumor‐immune cell interactions and supports the survival of patient‐derived stromal cells." (PMID 36417691, 2023). "Protein targets associated with B cells (CD20), NK cells (CD56), macrophages (CD68), and regulatory T cells (PD-1, FOXP3) were most differentially expressed in CD45+ segments within ‘immune-rich cancer cell islet’ regions of the tumor (cf. ‘surrounding stromal leukocyte’ regions)." (PMID 37046826, 2023).
tumor (continued). "Interestingly macrophage infiltration occurs early before tumor development, confirmed by immunohistochemistry of MMTV-Wnt+ and MMTV-Wnt- fat pads stained with CD68 and counterstained with Haemotoxylin (at 2,4,6 and 9 months of age)." (PMID 37449203, 2023). "Specifically, they found decreased infiltration of FOXP3+, CD68+, and PD1+ cells in para-tumor TLS." (PMID 38116013, 2023). "In advanced EOC patients, metformin treatment combined with platinum-based chemotherapy drugs reduces CD68+ macrophages in the tumor, however, with no statistical difference." (PMID 37686159, 2023). "Therefore, we investigated the expression of CD163+ TAMs, CD68+ M1s, CD8+ lymphocytes, and PD-L1 and CD25+ Treg cells within the primary tumours." (PMID 36857852, 2023). "In responders, the high-density areas of CD8+ and CD68+ cells seemed to be located more frequently in tumor tissue rather than in non-tumor tissue, and similar distribution patterns were observed within the same piece of tissue." (PMID 36694264, 2023). "The spatial, quantitative assessment of LAIR-1 in NSCLC shows positive association of OS with high LAIR-1+/CD68+ cell densities and negative association of OS with high LAIR-1 expression in LUAD tumor subtype." (PMID 36960400, 2023). "Furthermore, we also found a significant relationship between the density of TILs within the tumor nests and stroma, with the density of CD68+ and CD163+ macrophages infiltrating the tumor, and also with the tumor-infiltrating CD8+ T cells." (PMID 37893049, 2023). "The patient had multiple nonpainful nodular and tumour-like lesions, histiocytic infiltrates with emperipolesis were observed on histologic examination, and positive immunohistochemistry for CD68, and S100." (PMID 37799357, 2023). "NACT significantly increased infiltrates of CD4+Foxp3+ Treg cells (P = 0.036) and PD-L1+CD68+ macrophages (P = 0.022) in the stroma and decreased M1/M2 ratio (P = 0.016) in the tumor of CRS1 non-responders." (PMID 36993949, 2023). "The authors suggested that, in patients who achieved pCR under NAC, PD-L1 expression was significantly higher in tumor cells, CD68+ cells, and stroma than in nonpCR patients." (PMID 37284197, 2023). "For validation, IHC double stainings of PanCK/PD-L1, αSMA/PD-L1, and CD68/PD-L1 were performed showing that PD-L1 was more expressed by myofibroblasts and also macrophages rather than tumor cells." (PMID 37207152, 2023). "Indicating their origin from S100A9 MDSCs, it was also found that the percentage of blood S100A9 MDSCs was closely correlated with the counts of S100A9 cells and CD68 TAM in tumor tissue, and patients with higher S100A9 and CD68 cell numbers also showed worse PFS." (PMID 36817434, 2023). "Therefore, we used immunohistochemistry to evaluate the quantity and distribution of CD4+ lymphocytes, CD8+ lymphocytes, CD68+ macrophages, CD163+ macrophages, and M1-macrophages in the tumor center and invasion front in a cohort of 55 OSCC patients." (PMID 36836239, 2023). "Regarding the particular cell subtype of TAMs, it has been demonstrated the existence within the tumor of bipotent CD68+ and CD163+ cells capable of differentiating into both osteoclasts and macrophages with different effects on tumor progression and immunodepression." (PMID 36831348, 2023). "No matter PD-L1 was present or not, S15+ tumor cells were infiltrated by more CD68+ TAMs, and closer to CD68+ TAMs than S15− tumor cells." (PMID 37674198, 2023). "In addition to MCC tumor cells, we observed clusters of immune cells including CD4-positive and CD8A-positive T cells (clusters 7 and 11) and CD68-positive macrophages (cluster 16)." (PMID 36719743, 2023). "Notably, CD68+ TAMs infiltration level decreased significantly after NAC (stroma area: p = 0.025; tumor area: p = 0.028; total area: p = 0.013)." (PMID 36043478, 2023).